MMP3 (matrix metallopeptidase 3)
Diseases named in the same sentence as MMP3 in open-access papers (continued):
Sharing a sentence is not in itself a finding about the gene and the disease.
Stroke (continued). "Several inflammatory genes, like interleukin-6 (IL-6), tumor-necrosis factor-alpha (TNF-α) and matrix metalloproteinase-3 (MMP-3), were also found to confer risks for stroke." (PMID 23356535, 2013). "Studies of human brains report upregulation of both MMP-3 and MMP-9 following stroke." (PMID 39000490, 2024). "Females showed a larger negative enrichment score than males, but MMP-3 KO nevertheless downregulated integrin signaling gene expression signatures in both sexes during the subacute stroke phase, which correlated with reduced infarct volume." (PMID 39000490, 2024). "In contrast to MMP-9 and MMP-2 expression after r-tPA treatment in ischemic stroke, MMP-3 levels dropped post stroke without r-tPA treatment and further decreased following r-tPA treatment." (PMID 39273389, 2024). "Collectively, these findings demonstrate that MG-specific Nrf2 knockdown leads to augmented MMP3 and MMP9 expression in the ischemic brain, and that may subsequently result in aggravated BBB disruption after stroke." (PMID 39469715, 2024). "MMPs can degrade myelin and so the initial high production of MMP-2, MMP-3, and MMP-8 at 24 h following stroke may occur as a microglia/macrophage response to damaged myelin." (PMID 30417081, 2018). "miRNA-19a regulates MMP-3 via TLR2 and has angiogenic roles that may contribute to blood brain barrier breakdown and vascular remodeling post stroke." (PMID 24911610, 2014). "However, the molecular mechanisms through which MMP-3 inhibition improves stroke outcome independent of downstream MMP-9 and MMP-2 activation remain largely unexplored." (PMID 39000490, 2024). "This suggests that MMP-3 might not be involved in the degradation of the blood vessel barrier but related to neuronal cell death post stroke." (PMID 39273389, 2024). "In addition, we found that MMP3 and MMP9, which have been shown to play an essential role in promoting BBB disruption, were upregulated in the ischemic brains of MG-specific Nrf2 knockdown stroke mice compared to those of control stroke mice." (PMID 39469715, 2024). "However, male stroke brains with MMP-3 KO showed downregulation of genes in the neuroinflammation signaling pathway, while female MMP-3 KO stroke brains additionally showed downregulation of genes involved in the macrophage classical activation signaling pathway." (PMID 39000490, 2024). "In addition, the secondary mediators of ischemic cell death and blood-brain barrier disruption, such as IL-6, IL-1β, MMP-3 and iNOS, may constitute useful biomarkers of CKD-induced stroke severity." (PMID 31015533, 2019). "Indeed, expression of MMP-2 was 100-fold higher (4273 pg/mg), expression of MMP-3 was almost 3000-fold higher (15,059 pg/mg), and expression of MMP-8 was 500-fold higher (12,923 pg/mg) at eight weeks post stroke in the area of liquefactive necrosis compared to naïve brain tissue." (PMID 30417081, 2018). "Future studies should also investigate whether MMP-3 interacts directly or indirectly with estrogen receptors and androgen receptors in the nucleus to regulate gene expression in the brain; this may also account for some of our observed sex differences in response to MMP-3 KO following stroke." (PMID 39000490, 2024). "Although individual MMP expression had been examined at the prolonged time points, such as 24 h, 5, 7, and even 14 days, post stroke, MMP-9, MMP-3, and MMP-2 had not been compared simultaneously and we chose the 24 h time point to detect acute changes." (PMID 39273389, 2024). "In female MMP-3 KO mice, GSEA detected negative enrichment or downregulation of 64 genes related to apoptosis in the subacute stroke phase when compared to brains from WT controls (NES = −2.36)." (PMID 39000490, 2024). "In summary, although the exact roles of MMP3, FABP, and IL‐8 in hypothermia‐treated stroke patients are not known, these proteins should be explored in new studies testing systemic and also selective hypothermia." (PMID 37721534, 2023).
Stroke (continued). "Although the exact roles of MMP3, FABP, and IL‐8 in hypothermia‐treated stroke patients are not known, further exploration is needed to confirm their roles in brain ischemia." (PMID 37721534, 2023).
pulmonary fibrosis (32 papers, 2012 to 2025). Chronic progressive interstitial lung disorder characterized by the replacement of the lung tissue by connective tissue, leading to progressive dyspnea, respiratory failure, or right heart failure. "Among the identified candidate genes, the COL6A3, COL7A1, WNT5B, and MMP3 have been demonstrated to be associated with pulmonary fibrosis." (PMID 40034336, 2025). "We were particularly interested in the ECM associated genes and selected COL4A1, POSTN, MMP1 and MMP3 since they have been previously shown to be associated with pulmonary fibrosis." (PMID 33905434, 2021). "Conversely, MMP3 has a detrimental role in mouse models of acute lung injury and pulmonary fibrosis, with MMP3-deficient mice exhibiting less severe lung injury and protection from bleomycin-induced fibrosis." (PMID 33020210, 2020). "We also explored the potential mechanism that may be implicated in MMP-3-modulated Nano-CuO-induced lung fibrosis." (PMID 39030581, 2024). "Among them, MMP-3 has been associated with the development of pulmonary fibrosis." (PMID 39030581, 2024). "MMP3, for example, has been shown to be increased in idiopathic pulmonary fibrosis, and deletion of MMP3 protects mice from bleomycin-induced pulmonary fibrosis." (PMID 38473879, 2024). "We found in this model that circulating levels of CXCL9, DKK3, and MMP3 were already significantly elevated in day 18 samples, on average 10 days before the diagnosis of cGVHD, including pulmonary fibrosis." (PMID 37526081, 2023). "IL-17 increases MMP-3 activity in human epithelial cells, and MMP-3 is one of the major mediators of pulmonary fibrosis." (PMID 35363832, 2022). "Of note, further studies revealed that the MMP-3 level was mainly elevated in bronchial and alveolar epithelial cells, interstitial fibroblasts, alveolar macrophages, and other leukocytes of idiopathic pulmonary fibrosis (IPF) lungs." (PMID 35784288, 2022). "In particular, MMP-3 has been directly implicated in epithelial-mesenchymal transformation (EMT) and in the pathogenesis of pulmonary fibrosis." (PMID 35363832, 2022). "Mmp3 also promotes fibrosis by activating the β-catenin pathway and promoting epithelial-to-mesenchymal transition in idiopathic pulmonary fibrosis." (PMID 34830342, 2021). "MMP3 has been observed to be a mediator of pulmonary fibrosis, through activation of β-catenin signaling and induction of epithelial-mesenchymal transition." (PMID 26528997, 2015). "Recently, it was reported enhanced expression of MMP-3 in IPF, compared with control lungs and MMP-3-null mice were protected from bleomycin-induced pulmonary fibrosis." (PMID 23259796, 2012). "However, in mice treated with MMP-3 siRNA, the extent of Nano-CuO-induced lung fibrosis was much less than that in mice with control siRNA treatment." (PMID 39030581, 2024). "Interestingly, MMP-3, a member of MMPs and an important mediator of pulmonary fibrosis, is always co-expressed with OPN in fibrotic responses." (PMID 37217992, 2023). "MMP3, related to pulmonary fibrosis, is up-regulated in lung adenocarcinoma tissues." (PMID 36949111, 2023). "This raises the intriguing possibility that MMP-3-cleaved OPN induced by Nano-CuO exposure may be involved in Nano-CuO-induced pulmonary fibrosis." (PMID 37217992, 2023). "Both MMP3 and MMP7 appear critical to the development of experimental lung fibrosis, with rodents genetically deficient in MMP3 or MMP7 demonstrating a reduction in pulmonary fibrosis after bleomycin challenge." (PMID 32171287, 2020). "These experiments have established that miR-199a-5p is directly or indirectly involved in the regulation of genes previously associated with lung fibrosis: CCL2, a potent mononuclear cell chemoattractant, PLAU, a component of the fibrinolysis system, TGFBRI, the TGFβ receptor type I, MMP3 and CAV2." (PMID 23459460, 2013).
pulmonary fibrosis (continued). "Hence, the higher levels of MMP-3 found in our RA-ILD+ patients compared to those with IPF could be explained by the influence of both lung fibrosis and the inflammatory activity of RA." (PMID 39979794, 2025). "Moreover, mice with MMP3 knockout were protected from bleomycin-induced pulmonary fibrosis." (PMID 38976646, 2024). "Investigating the relationship between MMP-3-cleaved OPN and fibroblast activation after metal nanoparticle exposure has not been reported, which will contribute to our full understanding of the mechanisms underlying metal nanoparticle-induced pulmonary fibrosis." (PMID 37217992, 2023). "MMP-3, another member of the MMP family, has been shown to be involved in the development of pulmonary fibrosis." (PMID 39030581, 2024). "In the lungs of patients with idiopathic pulmonary fibrosis (IPF), elevated MMP-3 levels were observed, and the level of MMP-3 was related to the severity of pulmonary fibrosis." (PMID 39030581, 2024). "Mmp3 RNA and protein expression is correlated to human IPF disease and has been shown to mediate pulmonary fibrosis by activating the β-catenin pathway in lung epithelial cells." (PMID 38976646, 2024). "Some MMPs (MMP-3 and MMP-7) have been reported to induce EMT in lung fibrosis; however, the role of MMP-2 in EMT is unclear." (PMID 37047672, 2023). "High MMP3 levels have been reported in lung tissue from patients with IPF, and genetic deletion of MMP3 in mice abrogates bleomycin-induced pulmonary fibrosis." (PMID 31640794, 2019). "MMP-3 and MMP-7, in particular, have been shown to promote the EMT process during the development of pulmonary fibrosis." (PMID 26483688, 2015). "In animal models, adenoviral vector-mediated overexpression of MMP-3 resulted in the development of pulmonary fibrosis in rats, whereas mice lacking MMP-3 expression were protected from bleomycin-induced pulmonary fibrosis." (PMID 39030581, 2024). "Here, we hypothesized that exposure of human lung epithelial cells and macrophages to Nano-CuO would upregulate MMP-3, which cleaved osteopontin (OPN), resulting in fibroblast activation and lung fibrosis." (PMID 37217992, 2023). "In addition, TGF-β1 was proven to be an important regulator of MMP-3 and MMP-9 expression in the pulmonary tissues, which efficiently participate in the pathogenesis of lung fibrosis induced by chemotherapeutic agents." (PMID 38138222, 2023). "This theory is based on studies showing that MMP3 is upregulated in both IPF lungs and bleomycin-challenged mice and that MMP-3 knockout mice do not develop lung fibrosis after bleomycin challenge." (PMID 32485920, 2020). "Overexpression of MMP3 leads to pulmonary fibrosis in the rat lung, while mice lacking MMP3 are protected." (PMID 24279676, 2013). "Therefore, individuals with MMP3 rs522616 GG genotype may be not more vulnerable to permanent lung fibrosis due to the decreased MMP3 expression, with the reduced ability to degrade ECM." (PMID 26528997, 2015). "MMP-3-knockout mice and MMP-7-knockout mice do not develop pulmonary fibrosis induced by bleomycin, suggesting that MMP-3 and -7 may also act as mediators of pulmonary fibrosis." (PMID 26415518, 2015).
pancreatic cancer (30 papers, 1996 to 2025). "Increased MMP3 expression has been linked to poor prognosis and shorter overall survival in patients with breast, lung, and pancreatic cancers." (PMID 36765641, 2023). "To summarize, our results indicate that the Mmp3 was a weakly staining marker, and the staining pattern was not consistent across samples, thereby limiting its diagnostic value as a marker for pancreatic cancer." (PMID 36002889, 2022). "High MMP3 protein expression has been shown in breast, lung, and pancreatic cancer, and has been associated with poor prognosis." (PMID 32854182, 2020). "By revealing MMP3 staining to be strongly associated with epithelial tumor cells, our present findings suggest an autocrine MMP3-Rac1b signaling mechanism is involved in malignant progression of breast, lung, and pancreatic cancers." (PMID 26807201, 2015). "MMP3 initially collaborates with oncogenic KRAS to drive tumorigenesis in pancreatic cancer and activate the stromal microenvironment." (PMID 38612764, 2024). "During this process, we furtherly found that cordycepin, a selective MMP-3 inhibitor, had a satisfying effect in suppressing pancreatic cancer gemcitabine resistance." (PMID 36211828, 2022). "More study on the interaction between RRM1 and MMP-3 in pancreatic cancer is urgently needed in the future." (PMID 36211828, 2022). "In summary, our single-cell RNA sequencing and bioinformatics analysis identified several highly variable genes including IFI27, KRT18, KRT19, MMP1, MMP3, and NEFL, whose expression is associated with a shorter overall survival of pancreatic cancer patients." (PMID 36010660, 2022). "From clinical samples, bioinformatical results and cellular experiments, we found that MMP-3 expression was related to high glucose status in pancreatic cancer." (PMID 36211828, 2022). "Previous studies found that MMP-3 was regulated by ROS in many models, including pancreatic cancer cell model." (PMID 36211828, 2022). "High glucose elevates gemcitabine resistance via upregulating ROS levels to stimulate MMP-3 overexpression in pancreatic cancer cells." (PMID 36211828, 2022). "The 5-year survival of MMP3-high pancreatic cancer patients was 11%, while that of the MMP3-low expression group was 34%." (PMID 32260433, 2020). "Hypoxia induces expression of proangiogenic factor Vascular Endothelial Growth Factor (VEGF), Matrix Metallopeptidase-3 (MMP3), and inflammatory cytokine IL-6, all reported to induce invasiveness of pancreatic cancers." (PMID 29320425, 2018). "Using collagen-1 as a marker of stromal tissue, we observed that MMP3 and Rac1b were primarily expressed in the pancreatic tumor cells." (PMID 26807201, 2015). "In this study, we evaluate the stromal and epithelial cell expression of MMP3 in lung, breast, and pancreatic cancer." (PMID 26807201, 2015). "And this elevated ROS induced by gemcitabine may explain why MMP-3 was overexpressed in the naturally generated gemcitabine-resistant pancreatic cancer cells from another aspect." (PMID 36211828, 2022). "Interestingly, blocking MMP-3 had a better tumor-suppressive effect in gemcitabine-treated pancreatic cancer cells than blocking ROS." (PMID 36211828, 2022). "In pancreatic cancer, MMP-3 was reported to be related to cancer invasion and metastasis." (PMID 36211828, 2022). "ROS determined the MMP-3 expression in pancreatic cancer cells." (PMID 36211828, 2022). "MMP3 overexpression has been reported in PCa as well as breast, lung and pancreatic cancer cells, tissues and mouse models, it is hypothesised to aid invasion and metastasis via degradation of the ECM24–27." (PMID 29674723, 2018). "In this study we find that MMP3 and Rac1b proteins are both strongly expressed by the tumor cells of all three tumor types and that expression of MMP3 protein is prognostic of poor survival in pancreatic cancer patients." (PMID 26807201, 2015).
pancreatic cancer (continued). "Our studies to date of a large cohort of pancreatic cancer patients suggest that MMP3 staining may be useful as a prognostic tissue biomarker, and might be anticipated to predict response to therapies targeting this axis." (PMID 26807201, 2015). "Moreover, migration and invasion of pancreatic cancer cell lines (PANC-1 and SUIT-2) were associated with PDPN expression in CAFs (P < 0.01) and expression of CD10, matrix metalloproteinase (MMP) 2, and MMP3." (PMID 24354864, 2013). "Knockdown of MUC5AC reduced the ability of pancreatic cancer cells to adhesion and invasion, suggesting that MUC5AC might contribute to the invasive motility of pancreatic cancer cells by enhancing the expression of integrins, MMP-3, VEGF and activating Erk pathway." (PMID 20492722, 2010). "Most importantly, we demonstrate that MMP3 can be inhibited by the YAP/TAZ inhibitor verteporfin, which has entered clinical trials as a treatment for pancreatic cancer and glioma." (PMID 37834154, 2023). "We used two MMP-3 siRNAs (MMP-3_Si01 and MMP-3_Si02) and cordycepin, a selective MMP-3 inhibitor, to test the effect of blocking MMP-3 in pancreatic cancer cells." (PMID 36211828, 2022). "Our result showed that MMP-3 effectively blunted PDA gemcitabine sensitivity, which presented as reduced apoptosis and promoted proliferation in pancreatic cancer cells." (PMID 36211828, 2022). "Among all the proteins that were analyzed (MMP3, KIF5B, SFRP2, and LOXL2), KIF5B and SFRP2 show promise as bona fide early pancreatic cancer biomarkers expressed in progressive stages of pancreatic cancer." (PMID 36002889, 2022). "Knockdown of NR5A2 in pancreatic cancer decreased the expression of FGB, TWIST, SNAIL, MMP9, MMP3, MMP2, and Vimentin, as well as increased the expression of the epithelial markers β-catenin and E-cadherin." (PMID 34277436, 2021). "Collectively, our results demonstrate that miR-145 targets MMP3, as well as Oct4, Lin28, Nanog, Sox2 and ZEB1 which are upregulated by linc-DYNC2H1-4 in pancreatic cancer cells." (PMID 28703793, 2017). "Our data strongly suggest that linc-DYNC2H1-4 acts as a sponge of miR-145 to upregulate the expression of its targets, MMP3, Oct4, Lin28, Nanog, Sox2 and ZEB1, thereby promoting EMT progression and CSC formation in pancreatic cancer cells." (PMID 28703793, 2017). "Previous studies indicated that HOXA10 and HOXA11 regulate expression of MMP-3 and MMP-2, respectively, and both MMPs contribute to migration/invasion of pancreatic cancer cells." (PMID 25912306, 2015). "CD10+ PSCs produced higher amounts of matrix metalloproteinase 3 (MMP3) than CD10− PSCs, whose siRNA-based knockdown attenuated the invasive capacity of the pancreatic cancer cells." (PMID 24198790, 2013). "We have previously shown an upregulated expression of MMP-3 and MMP-9 in pancreas cancer tissue, and interestingly both these proteases have type IV collagen as a substrate." (PMID 19491897, 2009). "MMP3, a member of the MMP family, has been shown to induce migration of pancreatic cancer cells." (PMID 41050411, 2025). "Taken together, MMP3 and MMP7 might be involved in the migration and invasion of pancreatic cancer induced by YY1 targeting TPPP." (PMID 31631174, 2019). "Our results showed that MUC5AC down regulation suppressed several integrins, MMP-3 and VEGF, indicating that down-regulated MUC5AC in pancreateic cancer might reduce production of VEGF-A resulting in suppression of integrins and MMP-3." (PMID 20492722, 2010). "Therefore, MMP3 is a good candidate for pancreatic cancer detection but not for pancreatic cancer staging." (PMID 40292193, 2024). "Moreover, the NOX4 expression in pancreatic cancer cells did not showed an obvious change after being treated with 100 U MMP-3 in the GSE50931." (PMID 36211828, 2022).